GAD1 (glutamate decarboxylase 1)
Diseases named in the same sentence as GAD1 in open-access papers (continued):
Sharing a sentence is not in itself a finding about the gene and the disease.
neurological disorders (45 papers, 2011 to 2025). "Following the ascertainment of a further branch of the CPSQ1 kindred, we found that the previously reported GAD1 variant did not segregate with the neurological disease phenotype in the recently ascertained branch of the kindred." (PMID 33634263, 2021).
tumor (44 papers, 2011 to 2026). "In mice, B cell defciency or B cell-specifc inactivation of the GABA-generating enzyme GAD67 (GAD1 alleles) enhanced anti-tumour responses." (PMID 37904122, 2023). "In immunohistochemical analysis using our cohort, a positive cytoplasmic GAD1 staining pattern in tumor cells was significantly associated with poor prognosis, particularly DFS but not OS, in patients with LADC." (PMID 31207151, 2019). "Additionally, GAD1 expression, mutation and methylation were significantly correlated with the clinicopathological features and the tumor immune microenvironment." (PMID 37904122, 2023). "Glutamate decarboxylase 1 (GAD1), which mainly produces gamma-aminobutyric acid (GABA) in neurons, has also been implicated in tumor progression." (PMID 41844572, 2026). "Knockdown and pharmacological inhibition of GAD1 reduced tumor invasion, while exogenous GABA promoted invasion." (PMID 40851030, 2025). "A metastasis map of human cancer cell lines (MetMap) and functional studies using a microfluidic tumor-on-chip platform demonstrated that high GAD1 expression correlates with increased metastatic potential." (PMID 40851030, 2025). "Compared to the in vivo tumor data, morphine treatment showed a more profound reduction (50%) in GAD1." (PMID 40227606, 2025). "For instance, aberrant expression of glutamate decarboxylase 1 (GAD1) in tumor cells has been shown to mediate intrinsic resistance by promoting tumor cell proliferation via β-catenin activation." (PMID 41050070, 2025). "In conclusion, we demonstrated that miR-4284, which directly targets GAD1, affected tumor growth, metastasis, and apoptosis in RCC in vitro and tumor proliferation in vivo." (PMID 37568704, 2023). "For example, GAD1 expression is significantly upregulated in many tumor tissues, such as rectal cancer, breast cancer, lymphoma, and gastric cancer." (PMID 36814556, 2023). "Our study provided novel findings about the miR-4284 functions as a tumor suppressor in RCC by targeting GAD-1." (PMID 37568704, 2023). "GAD1 has been reported to stimulate tumor cell invasion and metastasis by regulating β-catenin translocation and activating MMP7." (PMID 36671437, 2022). "In the present study, we focused on GAD1 as a hypermethylated gene at specific CpG sites in LADC tumors and demonstrated its overexpression in tumor‐specific and methylation level‐associated manners in LADC." (PMID 31207151, 2019). "Furthermore, zebrafish xenotransplantation experiments demonstrated that GAD1 overexpression suppressed tumor growth, whereas GAD1 knockdown facilitated tumor formation." (PMID 41844572, 2026). "In a mouse model, knockout of GAD1 significantly slowed tumor growth." (PMID 40243466, 2025). "In addition, the levels of GABA-producing enzyme glutamate decarboxylase 1 (GAD1) are increased in tumor samples specifically from these patients." (PMID 40722337, 2025). "GABA significantly inhibited tumor growth by interfering the expression of GAD1 in tumor cells." (PMID 36618705, 2022). "Lung and colon cancer cells could metabolize and synthesize GABA by abnormal expression of GAD1, a member of the glutamate decarboxylase family, which were shown in many clinical samples of tumor patients, mouse tumor models, and in vitro tumor cells." (PMID 36618705, 2022). "Moreover, we assessed the prognostic significance of GAD1 expression in LADC using our tumor panel and publicly available datasets." (PMID 31207151, 2019). "Because the gene expression status appears to more directly contribute to the establishment of clinicopathological phenotypes in tumor cells, it is necessary to investigate the detailed regulatory mechanisms of GAD1 expression in LADC cells at each developmental stage of the tumor." (PMID 31207151, 2019). "In addition, tumor cells aberrantly expressing GAD1 could enhance the tumors immune suppressive function through autocrine action of GABA." (PMID 37277776, 2023).
tumor (continued). "Tumor cells achieve increased GABA synthesis through the aberrant expression of glutamate decarboxylase 1 (GAD1), inhibition of GAD1 reduces GABA production in tumor cells, thereby hindering tumor growth." (PMID 41583906, 2026). "Many therapeutic targets—such as GAD1, DAD1, and MMP9—are also expressed in normal tissues, raising concerns about off-tumor toxicity." (PMID 41050070, 2025). "In most peripheral solid tumors, elevated expression of GAD1 and downregulation of GABA-degrading enzyme ABAT in tumor cells lead to the accumulation of GABA in the tumor microenvironment, thereby promoting tumor growth and immune evasion." (PMID 40837580, 2025). "GABA concentration correlated significantly with expression of glutamate decarboxylase 1 (GAD1), an enzyme key to its synthesis, with both being particularly high in WNT tumours." (PMID 38184938, 2024). "In tumor samples from 10 HCC patients, PMVK, GAD1, and ACAT1 were significantly upregulated relative to matched normal liver tissues." (PMID 39325640, 2024). "Recent studies have demonstrated that GAD1 and GABA regulate tumor cell proliferation, especially that of stem cells." (PMID 36814556, 2023). "Then, glutamate is converted to γ-aminobutyric acid (GABA) by the rate-limiting enzyme glutamate decarboxylase 1 (GAD1), which is overexpressed in tumour tissues." (PMID 34917201, 2021). "GAD1, SPP1, and WFS1 were upregulated, whereas GOT2, EHHADH, and APOA1 were downregulated in HCC samples compared with peri-tumor controls, and this was consistent with the results in the ICGC, GSE14520, GSE54236, GSE107170, and GSE36376, validation datasets." (PMID 34869039, 2021). "Compared with peri-tumor samples, GAD1, SPP1, and WFS1 were significantly upregulated in tumor tissues, and GOT2, EHHADH, and APOA1 were significantly downregulated in tumor tissues." (PMID 34869039, 2021). "UALCAN analysis indicated that the transcription levels of GAD1, SPP1, and WFS1 were markedly higher in HCC tissues than in peri-tumor control tissues in the subgroup analyses." (PMID 34869039, 2021). "Additionally, GAD1, which regulates human sleep architecture by synthesizing the GABA-inhibitory neurotransmitters, facilitates tumor cell proliferation through GABA-mediated β-catenin activation." (PMID 40243466, 2025). "Previous studies have observed GAD1 upregulation and ABAT downregulation in tumor cells." (PMID 40837580, 2025). "Notably, glutamate decarboxylase 1, which is involved in GABA synthesis, was strongly correlated with high GABA levels and a strong characteristic of WNT tumours, suggesting a mechanistic connection." (PMID 38184938, 2024). "This is achieved by recruiting and activating GAD1 and ACAT1, leading to GABA accumulation, increased efficiency of 4‐Ac‐GABA synthesis, and the suppression of CD8+ T cell activation, intratumoral infiltration, and anti‐tumor responses." (PMID 39325640, 2024). "The expression of GAD1 (r = -0.14, P = 9.2E-03) and SPP1 (r = -0.237, P = 8.32E-06) was negatively correlated, whereas EHHADH was positively correlated (r=-0.15, P =5.36E-03) with tumor purity." (PMID 34869039, 2021). "This conclusion is further supported by analyses of the expression of GAD1, GSK3β, PKM2, and CPT1 in cervical lesions, and the results of these analyses imply that enhanced aerobic glycolysis and disturbed lipid metabolism are advantageous to tumor growth." (PMID 31465717, 2020). "The results showed that GSK3β and GAD1 were significantly downregulated and CPT1A and PKM2 were upregulated in CSCC compared with NC samples (p < 0.05), indicating that the catabolism of sugar and lipids was enhanced in tumor cells." (PMID 31465717, 2020). "Cytoplasmic GAD1 staining was observed in LADC tumor cells with higher mRNA expression, whereas nearly no staining was observed in normal lung epithelial cells and either tumorous or non‐tumorous epithelial cells in LADC with lower mRNA expression." (PMID 31207151, 2019).
tumor (continued). "In U-87MG cell-derived tumours, immunostaining for mature neuronal markers, including tubulin beta 3 (TUBB3) and glutamate decarboxylase 1 (GAD1/GAD-67), involved in GABA synthesis, revealed high expression levels in si-hVDAC1-TTs and low expression in the NT-TTs." (PMID 30544833, 2018). "Consistent with evidence in prokaryotic and eukaryotic organisms that GABA synthesis mediated through GAD1 may play a crucial role in surviving stress, GABA may be an important mediator of stress survival in neoplasms." (PMID 24551133, 2014). "And GAD1, NOS3, SERPINE1, and VWF protein levels were not significantly different in tumor and normal samples." (PMID 36860371, 2023). "Notably, GAD1 expression is upregulated in CRC cell lines and tumor tissues, while ABAT expression is downregulated, suggesting the accumulation of GABA in CRC may be attributed to elevated GAD1 and a lack of ABAT." (PMID 37610689, 2024). "Therefore, the methylation status of some CpG sites around GAD1 may contribute to its gene expression at some stages of LADC development, but not to the progression of this tumor." (PMID 31207151, 2019).
cancer (28 papers, 2012 to 2025). A tumor composed of atypical neoplastic, often pleomorphic cells that invade other tissues. "Gene expression analysis revealed that morphine downregulated GAD1, which encodes an enzyme essential for taurine synthesis—an amino acid known to counteract invasive cancer cell behavior." (PMID 40227606, 2025). "Further analysis indicated that GAD1 mutations were concentrated in the T2 stage (T2a and T2c) and middle-prostate, and that they were associated with a late cancer diagnosis and higher fraction genome alteration." (PMID 37904122, 2023). "Higher immunoreactivity of GAD1 was significantly associated with the pathological stage, pleural invasion, lymph vessel invasion, and poorer prognosis for cancer‐specific and disease‐free survival." (PMID 31207151, 2019). "GAD1 is activated by DNA methylation in cancer cells to increase its expression, which is pivotal for the development of mucinous colon cancer." (PMID 36814556, 2023). "Elevated levels of GABA in late-stage human tumors are inversely associated with prognosis, as are the expressions of GAD1 and GABABR, which are usually co-expressed in cancer cells, creating an autocrine signaling loop." (PMID 37324489, 2023). "Of potential relevance to cancer, treatment of these cells with endocrine disrupting agents induces a four-fold upregulation of GAD1 transcript levels (see the supplementary microarray data in Ref." (PMID 33187258, 2020). "Because the gene expression status of cancer cells directly affects their phenotypes, including malignant features, we focused on GAD1 expression in tumors to further assess its prognostic significance in patients with LADC." (PMID 31207151, 2019). "Epigenetic upregulation of glutamate decarboxylase 1 (GAD1) has been shown to program the aggressive features of cancer cell metabolism in brain metastatic microenvironment." (PMID 30626092, 2019). "Our results are further supported by studies documenting the proliferative effects of GABA on cancer cells, the expression of GAD1, and the expression of GABA receptors in multiple cancers throughout the body." (PMID 24551133, 2014). "We identified a total of 6 patients out of a total of 216 patients (2.8%) whose cancers displayed GAD1 overexpression with a z-score greater than +2." (PMID 24551133, 2014). "Patients with cancers that overexpressed GAD1 had a median disease free survival time of 19.8 months versus 110.3 months (p = 0.003)." (PMID 24551133, 2014). "Moreover, there was a statistically significant difference in the effect of GAD1 expression in cancer versus its paraneoplastic expression on the immune checkpoint blockade response and MSI scores." (PMID 37904122, 2023). "In contrast, GAD1 has been proved to be a cancer-promoting gene." (PMID 37904122, 2023). "In addition, GAD1 expression is significantly elevated in microsatellite unstable (MSI) colon cancer compared to microsatellite stable (MSS) cancer." (PMID 36814556, 2023). "In addition, in patients with RCC of all cancer stages, the higher the miR-4284 expression level and the lower the expression level of GAD1 (the target gene of miR-4284), the higher the OS." (PMID 37568704, 2023). "Furthermore, other researchers have shown that the GAD1 promoter is hypermethylated in a number of cancer cells." (PMID 30361509, 2018). "Here, we hypothesise that GAD1 may represent a better target in order to attenuate the incidence of cancer following COPD." (PMID 30361509, 2018). "We speculated that the GAD1/β-catenin/MMP7 interaction affects cancer cell behaviors, such as cellular invasiveness and migration." (PMID 24261884, 2013). "We then investigated MMP7 secretion, a downstream candidate of GAD1/β-catenin interaction, because MMP7 often is overexpressed in human cancer tissues and associated with cancer cell invasiveness by proteolytic cleavage of the ECM substrates and degradation of basement membrane proteins." (PMID 24261884, 2013).
cancer (continued). "In cancer cells, the TCA cycle is inhibited, and the GAD1-catalysed GAB inside mitochondria is accumulated, owing to the reprogramming of glucose metabolism." (PMID 38580938, 2024). "We also found the SRM, GAD1 and SMS were significantly elevated in contrast with those in paired normal samples in human cancers." (PMID 38637116, 2024). "According to the GAD1 protein expression status of LADC tumors, Kaplan‐Meier curves of estimated OS, disease‐free survival (DFS), and cancer‐specific survival (CSS) were generated." (PMID 31207151, 2019). "Extended morphine exposure appears to affect GAD1 expression and reduce taurine, specifically within the cancer tissue microenvironment, rather than exert systemic effects." (PMID 40227606, 2025). "The enzymatic functions of GAD1 and GAD2 are almost similar; however, their functions remain unclear in cancer tissues." (PMID 24261884, 2013). "Consequently, diminished GAD1 expression could impair taurine production locally, facilitating more acidic or immunosuppressive TME, which promotes cancer cell invasion and metastasis." (PMID 40227606, 2025). "This anti‐proliferative effect may be dependent on the presence of functional GAD, as in the absence of GAD1, higher concentrations of GABA promoted cancer cell growth." (PMID 38886975, 2024).
infection (25 papers, 2012 to 2025). The state of being infected such as from the introduction of a foreign agent such as serum, vaccine, antigenic substance or organism. "The gad1/2/4 triple and gad1/2/4/5 quadruple mutants showed enhanced susceptibility to both Pst and Pst‐avrRpt2 infection, but with differentially compromised resistance levels." (PMID 32458527, 2020). "In grapevine leaves, the activation of PR1, PR2, VvACO1, and GAD1 genes implies that the SA and JA pathways are involved in the development of resistance to pathogen infection." (PMID 38336608, 2024). "In order to get further insight into the role of GABA chemoperception during the infection process, we assessed virulence in A. thaliana gad1/2 mutant plants, which present reduced GABA levels." (PMID 35689388, 2022). "In response to Pst‐avrRpt2 infection, expression of GAD1 and GAD4 is induced, while expression of GAD2 is downregulated." (PMID 32458527, 2020). "In particular, in the gad1/2/4 and gad1/2/4/5 mutants the level of Ala was only ~30% of that in wild type after Pst‐avrRpt2 infection." (PMID 32458527, 2020). "In this report, we found that the gad1/2/4 triple and gad1/2/4/5 quadruple mutants, in which the GABA level is extremely low, are more susceptible to both Pst and Pst‐avrRpt2 infection, indicating a positive role of GABA in plant immunity." (PMID 32458527, 2020). "Further study is needed to determine if the reduced GABA levels in the gad1/2/4 triple and gad1/2/4/5 quadruple mutants might also impair stomatal closure during pathogen infection." (PMID 32458527, 2020). "We propose that the impaired primary metabolism could at least partially lead to the compromised resistance to pathogen infection of the gad1/2/4 triple and gad1/2/4/5 quadruple mutants." (PMID 32458527, 2020). "Both Pst‐avrRpt2 infection and activation of MPK3/MPK6 suppress GAD2 expression and induce the expression of GAD1/GAD4." (PMID 32458527, 2020). "Genetic evidence revealed that GAD1, GAD2, and GAD4 play important roles in both GABA biosynthesis and plant resistance in response to Pst‐avrRpt2 infection." (PMID 32458527, 2020). "Expression of GAD1 and GAD4 was significantly reduced in the mpk3 and mpk6 mutants compared to the levels seen in wild type, demonstrating that GAD1 and GAD4 upregulation is downstream of MPK3/MPK6 signaling during pathogen infection." (PMID 32458527, 2020).
psychiatric disorder (16 papers, 2012 to 2023). A disorder characterized by behavioral and/or psychological abnormalities, often accompanied by physical symptoms. "The methylation levels at this CpG site are associated with two variants within the GAD1 gene, suggesting an additional mechanism of how these SNPs affect the risk for different psychiatric disorders." (PMID 28094813, 2017). "PRKCE interacts with several proteins encoded by genes of potential relevance to psychiatric disorders, including the glutamate decarboxylases (GAD1, GAD2), NMDA receptors (GRIN2D, GRIN1), and a metabotropic glutamate receptor (GRM5)." (PMID 23922650, 2013). "The dysfunction of GAD67 in the brain is implicated in the pathophysiology of these psychiatric disorders; however, the neurobiological consequences of GAD67 dysfunction in mature brains are not fully understood because the homozygous Gad1 knockout is lethal in newborn mice." (PMID 33413507, 2021). "The GAD1 gene and GAD67 protein have often been targeted in human studies to elucidate an association with the pathophysiology of psychiatric disorders." (PMID 33413507, 2021). "The link between BDNF and glutamate decarboxylase 1 (GAD1)–γ-aminobutyric acid (GABA) signaling in the hippocampus is critical for the onset of psychiatric disorders." (PMID 33920851, 2021).
neurodegenerative disease (5 papers, 2018 to 2025). A disorder of the central nervous system characterized by gradual and progressive loss of neural tissue and neurologic function. "We provided a detailed characterisation of our cohort, including an analysis of biomarkers such as NfL, S100A9, kynurenic acid (KYNA), and GAD1, all of which are well documented in the literature for their importance in neurodegenerative diseases." (PMID 39767615, 2024).
brain disorder (3 papers, 2007 to 2022). A disease affecting the brain or part of the brain. "Subgenual anterior cingulate cortex (sgACC) of human subjects without brain disorders were labeled using fluorescent in situ hybridization (FISH) for CRH and markers of excitatory (SLC17A7), inhibitory (GAD1) neurons, as well as markers of other interneuron subpopulations (PVALB, SST, VIP)." (PMID 35280164, 2022).
adenocarcinoma (1 paper, 2014). A common cancer characterized by the presence of malignant glandular cells. "Interestingly, GAD1 mRNA expression was detectable only in castrate-resistant cell lines, with similar expression levels in the NCI-H660 NE cancer cell line and the PC3 and DU145 adenocarcinoma cell lines." (PMID 24551133, 2014).